STARD8 (StAR related lipid transfer domain containing 8)
Description:
Accelerates GTPase activity of RHOA and CDC42, but not RAC1. Stimulates the hydrolysis of phosphatidylinositol 4,5-bisphosphate by PLCD1.
Synonyms: DLC3; KIAA0189; ARHGAP38; STARTGAP3
Tractability: No criterion of Open Targets' tractability assessment is met for any kind of drug.
Gene: Protein-coding gene on chromosome X (68,647,666 to 68,725,842, forward strand). Ensembl gene ENSG00000130052.
Subcellular location: Cell junction, focal adhesion
Pathways (Reactome):
Signal Transduction: CDC42 GTPase cycle; RHOA GTPase cycle; RHOB GTPase cycle
Gene Ontology:
Molecular function: GTPase activator activity; lipid binding
Biological process: actin cytoskeleton organization; regulation of Rho protein signal transduction; signal transduction
Cellular component: focal adhesion
Homologues: Orthologues: chimpanzee STARD8 (99% identical), chimpanzee STARD8 (98% identical), macaque STARD8 (93% identical), pig STARD8 (88% identical), rabbit STARD8 (88% identical), dog STARD8 (84% identical), rat Stard8 (83% identical), mouse Stard8 (79% identical), tropical clawed frog stard8 (52% identical), zebrafish stard8 (49% identical), Caenorhabditis elegans gei-1 (24% identical). Paralogues in human: STARD13 (45% identical), DLC1 (43% identical).
Diseases named in the same sentence as STARD8 in open-access papers:
STARD8 is named in the same sentence as 14 diseases in open-access papers, as found by Europe PMC text mining. Sharing a sentence is not in itself a finding about the gene and the disease. The quoted sentences say what the papers report.
breast carcinoma (4 papers, 2013 to 2021). "DLC3 (STARD8) has been identified as a Cdc42 regulator whose levels are reduced, at the mRNA level at least, in kidney, lung, ovarian, uterine and breast cancer." (PMID 34196668, 2021). "Of note, in MCF7 breast cancer cells, STARD8 had a growth-promoting effect as opposed to its tumor-suppressive function in melanoma and lung cancer." (PMID 28423600, 2017).
Swyer syndrome (2 papers, 2024 to 2025). "Swyer syndrome may be caused by SRY mutation (10%–15%), FTHL17, STARD8, SOX9, MAP3K1, NR5A1, and desert hedgehog gene (DHH) mutation as well as other unidentified genes." (PMID 41163677, 2025). "Considering the risk of malignancy in gonads in patients with Swyer syndrome, the data suggest that some pathogenic variants (FTLHL17, DAX-1, DHH R124Q, del at 17q24.3) may be associated with a higher risk and some (STAR, STARD8, MAP3K1) with a lower risk of tumorigenesis." (PMID 38337479, 2024).
craniofrontonasal syndrome (1 paper, 2011). "A partial deletion of STARD8 is associated with the craniofrontonasal syndrome especially in females." (PMID 21668950, 2011).
lung adenocarcinoma (1 paper, 2015). A carcinoma that arises from the lung and is characterized by the presence of malignant glandular epithelial cells. "Three possible lung adenocarcinoma-related DEGs including ERG, STARD8 and THBS2 were identified." (PMID 26035298, 2015). "Therefore, STARD8 and THBS2 may also be involved in lung adenocarcinoma." (PMID 26035298, 2015).
ovarian carcinoma (1 paper, 2016). A malignant neoplasm originating from the surface ovarian epithelium. "No DLC3 copy number losses were found in any of the tumors examined in this study, although losses at the DLC3/STARD8 locus at Xq13 have been reported in ovarian carcinomas." (PMID 27174913, 2016).
tumor (7 papers, 2011 to 2024). "STARD8, a recently identified Rho GTPase-activating protein, exhibits downregulation in various malignancies and exerts inhibitory effects on tumor cell proliferation." (PMID 38052924, 2023). "One study reported a tumor suppressive role of STARD8, which is in accord with our results in A375 cells." (PMID 28423600, 2017). "Among the top five growth-suppressing genes tested, STARD8 and DUSP6, a commonly known tumor suppressor, arrested cells in G1/G0-phase, while MAPRE3, RPS6KA2 and EMD induced apoptosis." (PMID 28423600, 2017).
cancer (6 papers, 2009 to 2024). A tumor composed of atypical neoplastic, often pleomorphic cells that invade other tissues. "The deleted in liver cancer 1 (DLC-1 or STARD12), DLC-2 (STARD13), and DLC-3 (STARD8) RhoGAPs are frequently down-regulated in cancer and associated with poor prognosis." (PMID 33142932, 2020). "START domain containing LTP (LdBPK_292840.1) could regulate the cytoskeleton organization and motility of parasite, as START homologs (STARD8/12/13) are involved in cytoskeleton organization and migration of cancer cell line." (PMID 37445815, 2023). "STARD8 was identified as a tumor suppressor gene that inhibits cancer growth." (PMID 19750230, 2009). "STARD8/12/13 (START proteins with Rho-GAP domain) regulates the cytoskeleton organization and migration of a cancer cell line." (PMID 37445815, 2023).
genetic disorders (1 paper, 2011). "King and colleagues (2002) revealed that the StAR is expressed in glia and neurons of the mouse brain and has a role in the production of neurosteroids supporting STARD8 as a tentative biological role player in genetic disorders related to brain functioning." (PMID 21668950, 2011).
STARD8 also shares sentences with these, for which no sentence is quoted: lung carcinoma (3 papers); colon cancer (1); colorectal cancer (1); gonadal dysgenesis (1); melanoma (1); triple-negative breast carcinoma (1).